STAT3 (signal transducer and activator of transcription 3)
Diseases named in the same sentence as STAT3 in open-access papers (continued):
Sharing a sentence is not in itself a finding about the gene and the disease.
hepatocellular carcinoma (continued). "Another study also suggested that miR-383 may target IL-17 through the STAT3 signaling pathway and thus exert antitumor effects in hepatocellular carcinoma." (PMID 36553511, 2022). "However, an antiangiogenic and pro-apoptotic effect, through inhibition of vascular endothelial growth factor (VEGF), HIF-1α, Janus kinase/signal transducers and activators of transcription 3 (JAK/STAT3), was observed in liver carcinoma." (PMID 36077358, 2022). "The allele G was associated with an increased cervical cancer risk, and the risks of gastric cancer, hepatocellular carcinoma, and cancer in general were not altered by the STAT3 c.-1937C>G SNV." (PMID 35982955, 2022). "Furthermore, secretion of CXCL12/SDF1 by hepatic carcinoma-derived CAFs attracts monocytes into the tumor stroma and engages their differentiation into MDSCs in an IL-6- and STAT3-dependent manner." (PMID 36338519, 2022). "In addition, ICT downregulates the IL-6/JAK2/STAT3 pathway activity to inhibit hepatocellular carcinoma-initiating cells (HCICs) and effectively reduces the expression of HCIC markers, such as EpCAM, CD133, and CD24, in a dose-dependent manner." (PMID 35600861, 2022). "Further researches on molecular mechanisms showed that activated STAT3 pathway by IL-6 upregulated CD47 expression in hepatocellular carcinoma cell lines, and the IL-6-STAT3 axis blockage reduced cancer cells' antiphagocytic ability via downregulation of CD47 expression." (PMID 35281519, 2022). "In this regard, functional AQP3 and Nek2 is mutated or highly expressed in hepatocellular carcinoma, these molecular and cellular mechanisms may be overcome by the pharmacological action of AQP3/STAT3/CD133 pathway degradation and Nek2 inhibition." (PMID 35820920, 2022). "Moreover, IL-6-activated STAT3 condensates have also been observed in the cytoplasm of hepatoma cells; these are disrupted by 1,6-hexanediol and hypotonic stress." (PMID 35406728, 2022). "It has been reported that BMP10 significantly affected the STAT3 signaling pathway by facilitating dephosphorylation of STAT3 via protein tyrosine phosphatase sigma (PTPRS) in hepatocellular carcinoma, a previously unknown phosphatase of STAT3." (PMID 35293279, 2022). "Curcumol inhibits the production of programmed cell death-ligand 1 in hepatocellular carcinoma cells via the hypoxia-inducible factor-1 alpha and the signal transducer and activator of transcription 3 signaling pathways, restoring the tumor-killing capabilities of cytotoxic T lymphocytes." (PMID 35889217, 2022). "In addition, HBX can increase the transcription of LncRNA LINC01152 to enhance IL-23 expression and then initiate the activation of STAT3 to promote the proliferation and survival of hepatoma cells." (PMID 35251017, 2022). "Previous research has demonstrated that Sal B may restrain the migration and invasion of hepatocellular carcinoma through RECK/STAT3 signaling." (PMID 35502178, 2022). "Furthermore, p-STAT3 (Tyr705) is a major kinase-independent target of sorafenib in hepatocellular carcinoma, and dephosphorylation at Tyr705 enhances the therapeutic efficacy of sorafenib in glioblastoma." (PMID 36443287, 2022). "As Gadd45g-induced senescence in hepatocellular carcinoma cells depends on the activation of Stat3,27 we sought to determine whether an increase of Gadd45g reduced cell proliferation by repressing Stat3 activity." (PMID 35211358, 2022). "Artesunate disrupted tyrosine phosphorylation of STAT-3 in HepG2 hepatocellular carcinoma cells." (PMID 35267408, 2022). "Transmembrane phosphatase with tensin homology pseudogene 1 (TPTEP1) is a novel lncRNA that has been previously unveiled to repress tumor progression in hepatocellular carcinoma by hindering Signal transducer and activator of transcription 3 (STAT3) phosphorylation." (PMID 33985519, 2021).
hepatocellular carcinoma (continued). "In turn, activated STAT3 directly binds to the circLRIG3 promoter region, which enhances the circLRIG3 transcription, and at last, forms a positive regulatory circuit that improves hepatocellular carcinoma (HCC) processes." (PMID 34445958, 2021). "For instance, TAMs could enhance the proliferation of CSCs derived from hepatocellular carcinoma through IL‐6‐induced STAT3 activation." (PMID 33463006, 2021). "Moreover, STAT3-induced angiogenesis was also demonstrated in other types of cells, such as hepatocellular carcinoma." (PMID 33632325, 2021). "DDR1 induces EMT in hepatocellular carcinoma by regulating STAT3 in vitro and in vivo." (PMID 33917302, 2021). "We investigated whether LASP1 could enhance vimentin expression via the signal pathways and the results showed that over-expressed LASP1 could promote the activation of PI3-K, ERK, STAT3 pathways in hepatoma cells." (PMID 33722250, 2021). "Moreover, it has been shown that IL-22 promotes human hepatocellular carcinoma via activation of STAT3." (PMID 34941188, 2021). "Choudhari et.al show that deactivation of STAT3 can promote apoptosis in hepatocellular carcinoma." (PMID 34876150, 2021). "As we have shown in the previous sections, mortalin promoted the migration and invasion of hepatocellular carcinoma cells via RECK/STAT3 signaling, and Sal B inhibited EMT, the RECK/STAT3 pathway, MMP9/MMP2, and the migration and invasion of hepatocellular carcinoma cells." (PMID 34876128, 2021). "A previous study indicated that STAT3 could promote aerobic glycolysis through targeting hexokinase 2 in hepatocellular carcinoma." (PMID 34195079, 2021). "However, sesamin has the ability to suppress the STAT3 signaling pathway (IL6/JAK/STAT3) in human hepatocellular carcinoma cell line HepG2." (PMID 33578642, 2021). "As we have mentioned, being increased in the CD4+ and CD8+ subtypes in peripheral blood of patients with hepatocellular carcinoma, the p-STAT3 expression can lead to aberrant immunological surveillance, thus promoting the development of hepatocellular carcinoma." (PMID 33435880, 2021). "TAM-derived IL-6 and mitogens promote the occurrence and development of hepatocellular carcinoma via activation of signal transducer and activator of transcription 3 (STAT3) and nuclear factor kappa B (NF-κB) signaling, respectively, which also promote resistance to chemotherapy." (PMID 33802565, 2021). "CXCR2/CXCL5 axis could activate PI3K/AKT signaling in hepatocellular carcinoma cells and also activate the STAT3 signaling pathway to promote the migration and invasion in gastric cancer." (PMID 33458757, 2021). "Similarly, diosgenin (a compound present in the medicinal plant Trigonella foenum-graecum) has been shown to inhibit the growth of human hepatocellular carcinoma via inhibiting both inducible and constitutive activation of STAT3." (PMID 34078370, 2021). "A previous mechanistic study reported that IL-6 derived from TAMs could increase the expression of CD47 in hepatoma cells via activation of the STAT3 pathway." (PMID 34573091, 2021). "Furthermore, our results showed that PI3-K, ERK, and STAT3 pathways were responsible for vimentin expression mediated by LASP1 in HBX-positive hepatoma cells." (PMID 33722250, 2021). "in 2008 also showed that IL-6 could induce a growth arrest in rat hepatoma cells in a STAT-3-dependent manner through regulation of CDK activity." (PMID 35127527, 2021). "Likewise, Morusin induced apoptosis and inhibited angiogenesis in hepatocellular carcinoma cells by inhibiting the IL6/STAT3 signaling pathway." (PMID 34638959, 2021). "It has been shown that human hepatoma cells with high expression of sfALR in the cytoplasm, exhibited reduced Cyp7a1 mRNA level and lower production of BA, and this was attributed to activation of signal transducer and activator of transcription 3 (STAT3)." (PMID 34440614, 2021).
hepatocellular carcinoma (continued). "Moreover, artesunate significantly inhibited the proliferation of hepatoma cell lines via STAT3 inhibition and DR4 augmentation." (PMID 33757521, 2021). "Moreover, correlational analysis suggested that miR-337-3p levels were inversely related to STAT3 levels in hepatocellular carcinoma." (PMID 33292166, 2020). "Several studies reported that inhibition of the STAT3 signaling pathway reduced the expression of cyclin D1 and enhanced the drug sensitivity of the cancer cells, including gastric carcinoma, cholangiocarcinoma, bladder cancer and hepatocellular carcinoma." (PMID 32872659, 2020). "Moreover, our data showed that high STAT3 expression in hepatocellular carcinoma patients was correlated with shorter overall survival." (PMID 33292166, 2020). "Moreover, another study reported that STAT3-mediated miR-23a expression leads to decreased gluconeogenesis in hepatocellular carcinoma." (PMID 32492770, 2020). "Next, we explored the roles of STAT3 in hepatocellular carcinoma." (PMID 33292166, 2020). "An investigation on hepatocellular carcinoma indicated that G6PD could activate the STAT3 pathway to promote EMT and further favor cancer metastasis." (PMID 32028979, 2020). "However, in other cases, STAT3 has been shown to act upstream of Rac1, for example in the mesenchymal type movement of hepatocellular carcinoma (HCC) cells." (PMID 32915198, 2020). "Our results indicated that HO-1 is the antitumor gene induced by IL-6 through the IL-6/JAK/STAT3 pathways; moreover, a feedback circuit may exist between IL-6 and HO-1 in hepatoma cells." (PMID 32204510, 2020). "Moreover, miR-337-3p inhibition or STAT3 overexpression abolished the effect of hsa_circ_0006916 suppression on the progression of hepatocellular carcinoma cells." (PMID 33292166, 2020). "Similarly, STAT3, a transcriptional corepressor, can bind to the miR-146a promoter and induce its expression in hepatocellular carcinoma cells." (PMID 32226532, 2020). "Then, we determined whether hsa_circ_0006916 regulated hepatocellular carcinoma progression through the miR-337-3p/STAT3 axis using qRT-PCR and western blotting." (PMID 33292166, 2020). "However, in many cases, frame deletionmutations in Gp 130 and point mutations in Jak2 promote the ligand-independentactivation of STAT-3 found in hepatocellular carcinomas." (PMID 32167126, 2020). "For instance, through secretion of IL-6, CAFs derived from human hepatocellular carcinoma are able to upregulate the activation of the STAT3 signalling pathway in DCs, which in turn, induces a regulatory DC phenotype which is unable to prime and activate T cells." (PMID 32967079, 2020). "Thus, we suggest that hsa_circ_0006916 overexpression promoted hepatocellular carcinoma progression through upregulating STAT3 expression as a miR-337-3p sponge." (PMID 33292166, 2020). "In the subcutaneous HCC model, we confirmed that the miR‐125b‐5p‐loaded nanomedicine enabled precise in vivo transfection of the miR‐125b‐5p plasmid and activation of the miR‐125b‐5p/STAT3 axis in hepatoma cells through RT‐PCR assay, western blot assay, and tumor growth curve assays." (PMID 31065520, 2019). "The results indicated that brevilin A suppressed the STAT3/Snail pathway in hepatoma cells." (PMID 35547606, 2019). "Additionally, in HCCLM3 hepatocellular carcinoma cells, the isoprenoid antibiotic ascochlorin increased the sensitivity to doxorubicin treatment by directly inhibiting binding of STAT3 to SNAI1 promoter." (PMID 31141910, 2019). "Interestingly, others have found that hsa-miR-637 expression leads to downregulation of STAT3 activity in hepatocellular carcinoma cells and STAT3 is one of the downstream activated proteins of c-MET activity." (PMID 31063487, 2019). "CXCL2 could also activate the STAT3 signalling pathway, which then regulates PD-L1 expression, in hepatocellular carcinoma cell lines." (PMID 31462002, 2019).
hepatocellular carcinoma (continued). "Next, whether AQP3 acted as an oncogenic gene in HCC and maintained the stemness of CD133+ hepatoma cells were elucidated; also, a novel mechanism underlying the AQP3/STAT3/CD133 pathway in HCC was deduced." (PMID 31197130, 2019). "In addition, it was also found to promote hepatocellular carcinoma progression by repressing FOXO3a or promoting glioma tumorigenesis by STAT3 activation." (PMID 31605468, 2019). "IL6R increased BCL-2 and STAT3 in hepatocellular carcinoma (HCC)." (PMID 31484561, 2019). "In addition to this role in hepatocellular cancer, STAT3 activation plays a role in EMT induction in different types of tumors." (PMID 29588647, 2018). "Similarly, PML is known to modulate interleukin (IL)-6-induced STAT3 activation and hepatoma cell growth by interacting with HDAC361." (PMID 30143675, 2018). "miR-155 was reported to promote invasiveness of pancreatic cancer cells, through regulating suppressor of cytokine signaling 1 (SOCS1) and P-signal transducer and activator of transcription-3 (STAT3), and promote the hepatocellular carcinoma progression by targeting PTEN." (PMID 30046565, 2018). "Previous studies have revealed that SCU could induce apoptosis and suppress migration and invasion of human hepatocellular carcinoma by inhibiting the STAT3/Girdin/Akt signaling pathway." (PMID 29962947, 2018). "Furthermore, upregulation of miR-500a-3p promoted, while silencing miR-500a-3p repressed, the CSCs-like phenotypes in vitro and tumorigenicity in vivo in hepatocellular carcinoma cells via STAT3 signaling." (PMID 28750679, 2017). "DUSP22 has been shown to be induced by the pro-inflammatory cytokine interleukin-6 (IL-6) and could dephosphorylate STAT3 in hepatoma cells, creating a feedback loop for the IL-6/STAT3 signaling." (PMID 28902166, 2017). "Therefore, our findings suggest that miR-340-5p inhibits the migration of hepatoma cells via targeting of the STAT3 gene." (PMID 28413603, 2017). "STAT3 plays an important role in the differentiation and tumorigenesis of hepatocellular carcinoma." (PMID 29226125, 2017). "Moreover, miR-26a suppresses the IL-6-induced growth and metastasis of hepatocellular carcinoma by inhibiting STAT3." (PMID 28388577, 2017). "Previous studies reported that icaritin activates the JNK signaling pathway to promote apoptosis in hepatoma cells, and inhibits the IL-6/Jak2/Stat3 pathway to suppress HCC initiation and malignant growth by inducing the expression of anti-apoptotic factors of the Bcl-2 family." (PMID 27835879, 2016). "It will be interesting to investigate whether long-term activity of the JAK/STAT3 pathway affects hepatocyte/hepatoma cell metabolism in a different way." (PMID 26889381, 2016). "Emodin suppresses activation of JAK/STAT signaling in leukemia cells by inhibiting the kinase CK2, inhibits interleukin-6-induced JAK2/STAT3 signaling in myeloma cells, and suppresses STAT3 activation through upregulation of SHP-1 in hepatocellular carcinoma cells." (PMID 26683360, 2016). "Accordingly, recent proteomic results have demostrated that PI3K-dependent STAT3 activation may be also mediated by other molecules such as the tyrosine kinase expressed in hepatocellular carcinoma kinases (TEC)." (PMID 26486080, 2015). "Moreover, the IL-8 neutralizing antibody down-regulated Ser727-phosphorylated STAT3 levels in hepatoma cells treated with a-HSCs conditioned medium." (PMID 26593962, 2015). "Furthermore, the IL-8 neutralizing antibody partially attenuated the ability of HSC-CM to induce angiogenesis and down-regulated Ser727-phosphorylated STAT3 levels in hepatoma cells." (PMID 26593962, 2015). "Moreover, Ser727-phosphorylated STAT3 was effectively inhibited in HSC-CM-treated hepatoma cells by the IL-8 neutralizing antibody, whereas HIF-1α and NF-κB p65 activation was not affected." (PMID 26593962, 2015).
hepatocellular carcinoma (continued). "Therefore, other signals triggered by ConA in hepatoma cells are required to induce STAT3 phosphorylation and cell death, which remain to be investigated." (PMID 26633714, 2015). "In addition, ERp57 has been reported to interact with the STAT3 complex, enhancing STAT3 activity in melanoma and hepatoma cells, whereas another group suggested that this ERp57-STAT3 complex negatively affects STAT3 DNA-binding activity." (PMID 25605256, 2015). "Since γ-T3 also induce SHP-1 expression to inhibit STAT3 signaling in myeloma and hepatocellular carcinoma cells, both γ- and δ-T3 may function in a similar way to inhibit STAT3 signaling by inducing SHP-1 expression." (PMID 25849286, 2015). "Furthermore, we showed that a-HSCs promoted angiogenesis via IL-8 by up-regulating Ser727-phosphorylated STAT3 levels in hepatoma cells." (PMID 26593962, 2015). "However, the regulation of STAT3 transcriptional activity by STATIP1 was only observed in the human hepatocellular carcinoma cell line HepG2." (PMID 25417721, 2014). "In addition, scoparone inhibited proliferation of hepatoma, cervical cancer and colon cancer cell lines that harbor constitutively active STAT3." (PMID 24260381, 2013). "In addition to JAK-1, IL-6/JAK-2/STAT3 activation and tumor progression in hepatocellular carcinoma has recently been reported." (PMID 23555719, 2013). "Importantly, abrogation of constitutive STAT3 activity significantly sensitizes hepatocellular carcinoma cell lines to TRAIL." (PMID 24213315, 2012). "Numerous studies have illustrated that the JAK/STAT3 pathway is constitutively active in hepatocellular carcinoma (HCC) and is involved in the development and progression of this disease." (PMID 40001488, 2025). "In light of the pivotal role of inflammation in driving hepatocellular carcinoma progression, we next sought to determine whether the anti‐cancer effect of FPHPE involves modulation of the JAK2/STAT3 pathway—a central mediator of tumor‐associated inflammation and survival." (PMID 41200213, 2025). "Additionally, exosomal S100A4 plays a key role in hepatocellular carcinoma metastasis, by activating STAT3 phosphorylation and upregulating osteopontin expression, as well as inducing immunosuppression and non-small cell lung cancer development through STAT3 activation." (PMID 41002392, 2025). "Reduced GNAI1 expression has been reported in hepatocellular carcinoma, where it is associated with increased tumor cell migration and invasion, as well as in colorectal cancer metastasis, where its loss enhances angiogenesis through activation of JAK2/STAT3 signaling and upregulation of VEGFA." (PMID 41550951, 2025). "HBV-induced mitochondrial ROS overproduction enhances the activation of STAT3 and hepatocellular carcinoma (HCC) development." (PMID 41488475, 2025). "The resulting HBV-induced ROS accumulation promotes hepatic inflammation through IL-6 upregulation in hepatocellular carcinoma (HCC), concurrently driving constitutive STAT3 activation." (PMID 40918255, 2025). "In hepatocellular carcinoma (HCC), M2-polarized tumor-associated macrophages (TAMs) promote EMT and cancer cell migration via the TLR-4/STAT3 signaling pathway." (PMID 40404908, 2025). "A 75-year-old female with metastatic hepatocellular carcinoma (HCC) developed a grade 3 morbilliform eruption on her trunk and extremities 10 days after starting STAT3 inhibitor treatment." (PMID 40606688, 2025). "Oleocanthal inhibited the metastasis and tumor growth of hepatocellular carcinoma (HCC) by deactivating STAT3 in both in vivo and in vitro studies." (PMID 40979569, 2025). "The modulation of lipid metabolism through interaction with fatty acid-binding proteins and suppression of stearoyl-CoA desaturase (SCD) expression in lung cancer, and induction of ferroptosis via STAT3 inhibition in hepatocellular carcinoma (HCC)." (PMID 40758729, 2025).